GFAP (glial fibrillary acidic protein)
Diseases named in the same sentence as GFAP in open-access papers (continued):
Sharing a sentence is not in itself a finding about the gene and the disease.
tumor (continued). "In addition, the system effectively modulates the tumor microenvironment, significantly reducing GFAP-expressing reactive astrocytes while favorably redistributing M1/M2 macrophage populations." (PMID 41560805, 2026). "Three-dimensional imaging of colonic adenocarcinomas revealed that S100β+ GFAP+ enteric glial cell bodies and processes extensively infiltrate the tumor mass, including direct interactions between EGCs and tumor-associated macrophages within the CRC microenvironment." (PMID 41463087, 2025). "We provided hitherto undocumented evidence that lactate in hypoxic tumor microenvironment (TME) could initiate GFAP-dedifferentiation of SCs, and the latter enhanced dCCA progression through upregulating high mobility group box 1 (HMGB1)." (PMID 40148311, 2025). "Concurrently, severe GFAP expression was observed in astrocytes surrounding the tumor." (PMID 39821858, 2025). "GFAP and vimentin are often expressed in DMGs, reinforcing their astrocytic lineage, while the Ki-67 proliferation index is typically high, indicating rapid tumor growth." (PMID 40937216, 2025). "Interestingly, we found an enrichment of astrocyte and cell proliferation related terms in NMF_2 and NMF_3 and the top genes include SLC1A3 and GFAP, markers of the previously defined “AC-like” tumor cell state." (PMID 40781324, 2025). "Also, the pronounced activity of the GFAP marker was determined with great consistency both in the central areas of tumor cell complexes and in marginal sections." (PMID 41148834, 2025). "Within the human tumor tissue, GFAP immunoreactive cells were observed in different locations." (PMID 40580485, 2025). "Interestingly, GFAP expression has also been observed in MB tumor cells themselves, particularly in the SHH subgroup, and is associated with heterogeneous clinical outcomes." (PMID 40805120, 2025). "Histological and immunohistochemical analyses confirmed the tumor’s myofibroblastic origin, characterized by positivity for markers such as vimentin, glial fibrillary acidic protein (GFAP), nerve growth factor receptor (NGFR), alpha-smooth muscle actin (SMA), and muscular actin (HHF35)." (PMID 40559758, 2025). "However, our immunofluorescence analyses using GFAP and Iba-1 confirmed robust glial and microglial activation in tumor-bearing groups, strongly indicating successful tumor engraftment." (PMID 40855299, 2025). "The findings presented in the current study also demonstrate a dose-dependent reduction in Ki67, Nop10, and H2AX expressions in tumor cells around blood vessels, alongside GFAP expression, following treatment with BA in astrocytes surrounding the tumors in rat GBM model." (PMID 39821858, 2025). "Tumor cells exhibited variable immunoreactivity for GFAP and were positive for Olig2." (PMID 40469416, 2025). "In addition, cases with tumor recurrence or progression had a higher number of GFAP+ tumor cells (U-Mann–Whitney, p = 0.04)." (PMID 40805120, 2025). "However, this GFAP+ EV strategy is still limited in its ability to differentiate tumor-derived EVs from non-tumor astrocytes." (PMID 41373835, 2025).
tumor (continued). "Interestingly, double positive cells were scarcely detectable in sh-DUSP8-GFP tumor where instead tumor cells resulted surrounded by mouse reactive glia cells, GFAP+ GFP− cells, suggesting a strong reaction of mouse brain parenchyma." (PMID 41029387, 2025). "GFAP signal, mainly localized at the tumor border in vehicle treated animals, was reduced by RT." (PMID 40520013, 2025). "Notably, tumor cells generally express GFAP and S-100, with the molecular alteration identified as the RREB1-MKL2 fusion." (PMID 39995845, 2025). "To focus on changes occurring specifically in myeloid and neoplastic cells, we performed spatial transcriptomics analysis on GFAP+ cells (tumor cells, astrocytes) and CD64+ cells to gain a more granular understanding of myeloid/tumor transcriptional state changes on the path from pGBM to rGBM." (PMID 39423857, 2025). "Additionally, the GFAP + PTX scaffold determined a statistically significantly higher cytotoxicity compared with GF + PTX (p < 0.05), suggesting the ability of GFAP to deliver the anti-tumor drug with higher efficiency." (PMID 39940603, 2025). "From a pathological standpoint, the histogenesis of this tumor remains unclear, although strong GFAP positivity supports a likely glial origin." (PMID 41333225, 2025). "GFAP+ cells (astrocytes) were seen in the areas of infiltrative tumor." (PMID 41009470, 2025). "Tumor cells typically showed strong immunoreactivity for GFAP and Olig2." (PMID 40469416, 2025). "Interestingly, astrocytic GFAP expression also decreased in the prefrontal cortex of these BALB/c mice, suggesting an altered neuroinflammatory state caused by tumour burden." (PMID 40172096, 2025). "Particularly, three-dimensional imaging on full-thickness human colon adenocarcinomas using the iDISCO (immunolabeling-enabled imaging of solvent-cleared organs) staining, confirmed that S100β+ GFAP+ enteric glial cell bodies and projections massively infiltrate the whole tumour." (PMID 38957473, 2024). "Interestingly, EVs from all the tumor cell lines induced higher GFAP expression in astrocytes compared to PBS control treatment, indicative of an activated—or perhaps reactive—astrocyte state." (PMID 39585062, 2024). "GFAP and neurofilament were expressed in a subset of tumor cells in 2/5 cases examined." (PMID 38500181, 2024). "The tumour cells will express markers of glial differentiation (e.g. GFAP)." (PMID 39294363, 2024). "Treatment with CHA could reduce the expression of Ki67 in the tumor and increase the expression of GFAP, with increase the expression of CHKα and CCTα." (PMID 39494339, 2024). "Tumors were stained for C3, GFAP as an astrocytic marker, and Olig2 for the bulk of tumor cells." (PMID 39172519, 2024). "However, our spatial analysis of patient specimens shows increased MT3 expression and expression of the reactive gliosis marker GFAP at the tumor/stroma interface." (PMID 38866016, 2024). "Immunohistochemistry revealed that the tumor exhibited focal GFAP immunoreactivity." (PMID 38216991, 2024). "It is possible that any immediate effects from radiotherapy on biomarker levels could have been masked by effects of intracranial surgery as well as GFAP expressed by the tumor tissue itself." (PMID 39030984, 2024). "Definitive diagnosis hinges on the histopathological examination of the excised tumor, emphasizing the identification of infiltration and positivity for glial fibrillary acidic protein (GFAP), coupled with significant pleomorphism, rapid mitotic activity, microvascular proliferation, and necrosis." (PMID 38675903, 2024). "Additionally, GFAP and IBA1 staining visualized astrocytes and tumor-associated microglia/macrophages (TAMs), respectively, with a distribution mirroring real GBM tissue." (PMID 39594703, 2024).
tumor (continued). "Astrocytes also clustered into two distinct patterns, with Astrocyte_A cells showing lower expression of GFAP and localizing to distant brain areas outside of the tumor, while Astrocyte_B cells showed higher expression of GFAP, and localized to the border regions of both PDGfp and BrM tumors." (PMID 38622132, 2024). "Selection of regions of interest (ROIs) in participant FFPE tissue was guided by immunofluorescent staining of CD163 for myeloid cells (some macrophages, MDSC, microglia), CD3 (T lymphocytes), and GFAP (tumor and astrocytes) in conjunction with an expert neuropathologist." (PMID 39346903, 2024). "Indeed, approximately 34% of patients with GFAP astrocytopathy were diagnosed with neoplasms either at the time of presentation or in the years that followed." (PMID 39449321, 2024). "Furthermore, reducing GFAP expression in the tumour tissue after treatment suggests a favourable therapeutic outcome." (PMID 39629119, 2024). "There was no brain parenchyma invasion (no irregular infiltration or protrusion of tumor cells into the underlying GFAP‐positive parenchyma)." (PMID 38565263, 2024). "In addition, the different cell populations found in the T18_IM RB derived stromal cell line were successfully separated using MACS separation for tumor-associated macrophages (CD163 + CD68) and glia (GFAP)." (PMID 39695086, 2024). "In addition, the stiff tumor showed a proliferation of αSMA-positive spindle cells but tended to be fewer GFAP-positive glial cells than control tumors." (PMID 39186169, 2024). "Immunohistochemically, tumor cells express glial markers (i.e., GFAP and OLIG2) and CD34, which may be patchy or diffuse and may also display non-neoplastic ramified neural elements in the associated cerebral cortex." (PMID 38544524, 2024). "Importantly, GFAP ectopic expression by neoplasms has been thought to trigger an immune response resulting in a paraneoplastic autoimmune reaction directed against the self-antigen (GFAP)." (PMID 39449321, 2024). "Accordingly, we could segment GFAP-positive astrocytes surrounding the tumor and classify them according to their distances from the tumor cells." (PMID 38775133, 2024). "This was revealed by ASCL1’s ability to promote an increase in early migration of newly transformed GFP+ tumor cells out of the SVZ at P4 into the striatum, corpus callosum, and cortical plate of Ascl1-OE mice prior to their specification into either GFAP+ or SOX10+ tumor cells." (PMID 39609428, 2024). "Some of the tumour cells may be overtly neuronal, and this is reflected in the immunophenotype which shows a mixture of glial markers (e.g. GFAP) and neuronal markers." (PMID 39294363, 2024). "Various immunostaining evaluations were performed, and staining with an anti-GFAP antibody revealed scattered tumor cells in the i-PDT group outside of the necrotic area around the light source, which had a spherical morphology with shortened tumor cell processes and a condensed cytoplasm." (PMID 39335654, 2024). "Similarly, a reduction in tumour burden was also observed following the depletion of GFAP+ EGCs in an AOM/DSS-induced CRC mouse model." (PMID 38957473, 2024). "Immunohistochemically, the tumor was positive for glial fibrillary acidic protein (GFAP)." (PMID 36647049, 2023). "We observed GFAP+ cells with elongated shape in the region adjacent to GBM tumor mass (labeled as PT region), while GFAP+ cells far away from GBM exhibited star shapes (labeled as AT region), which was compatible to observation in our assembloid and mouse xenograft model." (PMID 37468961, 2023). "Of note, tumor exhibited a heterogeneous phenotype with a tumor component displaying glial differentiation, with robust GFAP expression, and a component with conventional MB features and selective presence of GNAS mutation, suggesting co-existence of two different major tumor subclones." (PMID 36941703, 2023).
tumor (continued). "Immunohistochemical analysis showed that the restricted tumor expressed GFAP." (PMID 37016352, 2023). "On the other hand, when performing immunohistochemistry using Nestin as a marker to identify GBM cells, tumor cells (Nestin + ) presented strong reactive gliosis given the co-distribution of Vimentin (green) and GFAP (white) in the control, IKE and IKE + DHAA+Lpx conditions in the tumor area." (PMID 37752118, 2023). "Interestingly, we observed weak positive GFAP staining within the tumor, both in GL261-CIITA and in parental tumors, while a reactive, dense, and more marked peritumoral astrocytosis was present in GL261-CIITA compared to GL261 parental tumor." (PMID 36993983, 2023). "Notably, in the opposite hemisphere, GFAP was markedly expressed and distributed around the tumor bed (pre-vaccinated, tum WT, black arrowheads)." (PMID 36993983, 2023). "Interestingly, we found IBA1+ cells presented both inside and outside GBM tumor, while GFAP+ cells mainly accumulated surrounding tumor mass." (PMID 37468961, 2023). "GFAP staining showed strong positivity of the tumor cell matrix with variable cytoplasmic reactivity between the cases and/or different areas within the same tumor." (PMID 36933012, 2023). "Moreover, additional morphological changes occurred on GFAP+ cells at DoCs 31 and 37, which changed from small and rounded to elongated, suggesting a glial infiltration around the tumor." (PMID 37190034, 2023). "We observed IGFBP2 throughout the tumor, including in GFAP-positive astrocytes." (PMID 37029430, 2023). "BI by meningioma is defined as tongue-like protrusions of tumor cells into underlying GFAP-positive cortical parenchyma, without intervening leptomeningeal layer at the tumor-CNS interface." (PMID 36811765, 2023). "The presence of vimentin and GFAP peptide fragments together, as well as their citrullinated forms, mainly characterized tumor tissues of lower World Health Organization (WHO) grades, such as pilocytic astrocytoma and ependymoma, while they were negligible in the most aggressive medulloblastoma." (PMID 37761239, 2023). "GFAP staining showed a significant reduction of GFAP+ cells within the tumour mass and in normal brain tissue after deserpidine treatment, as well as a trend towards reduction in normal tissue close to the tumour edge." (PMID 37759347, 2023). "The exception to this is tumours that exhibit very low GFAP expression." (PMID 35919979, 2022). "This suggests that in addition to tumour necrosis, GFAP may also be produced because of astrocyte damage in the brain surrounding the tumour." (PMID 35919979, 2022). "Using scRNAseq data from patient samples of primary and recurrent GBM (GSE154975), we identified multiple cell types based on markers from the original study: macrophages (ITGAM), T cells (CD3E), Tregs (CD4, CD3E, FOXP3), low-reads/dying cells (MALAT1), and tumor/normal brain cells (GFAP, SOX2)." (PMID 36591276, 2022). "Moreover, immunostaining of C3aR on MB tumor sections also showed that C3aR was mainly expressed on astrocytes (GFAP +) as well as microglia (Iba-1 +) in murine and human tumor tissue." (PMID 35725556, 2022). "The tumor is GFAP- and vimentin-positive with minimal positivity for CD3-positive T cells." (PMID 35446393, 2022). "The tumor cells lacked astrocytic processes while focal areas, immunohistochemically positive for glial fibrillary acidic protein (GFAP) and microtubule-associated protein 2 (MAP2), were interpreted as entrapped preexistent central nervous system tissue." (PMID 35198980, 2022). "Immunohistochemistry showed GFAP positive tumor cells with only short processes." (PMID 35018523, 2022). "In most cases, the GFAP levels scale with tumour severity and so several different cut-off limits may be implemented." (PMID 35919979, 2022). "Indeed, serum GFAP levels are correlated with tumor volume and histopathological tumor characteristics." (PMID 35806478, 2022).
tumor (continued). "In the future, it may be possible to quantify heterogeneities and incorporate errors into our models and predictions for GFAP blood levels for different tumours." (PMID 35919979, 2022). "Many tumor cells expressed GFAP and MAP2 in the cytoplasm and in processes." (PMID 35198980, 2022). "Glial markers, Olig2 and GFAP, were expressed in both tumour types." (PMID 36264505, 2022). "However, GFAP concentrations are extremely heterogenous across different tumours; for example, small tumours have been observed with very large serum GFAP concentrations and vice versa." (PMID 35919979, 2022). "The periphery of the tumor (reactive border) presented a strong staining for GFAP." (PMID 35402232, 2022). "Immunohistochemistry showed GFAP positive tumor cells with long processes." (PMID 35018523, 2022). "As the maximum tumour and necrotic size is reached, the GFAP levels may decrease as the rate of necrosis slows." (PMID 35919979, 2022). "Histology/immunohistochemistry showed collagenized septa with a small cell population with a high N/C ratio, pleomorphism, increased mitotic activity, strong INI-positivity, GFAP positivity, and a high Ki-67 index in cellular components of the tumor that further confirmed the diagnosis." (PMID 36333774, 2022). "Previous studies have found a correlation between tumour volume and serum GFAP levels." (PMID 35919979, 2022). "Given the emerging effects of glia-derived WNT ligands on the intestinal epithelium, it is interesting that depletion of GFAP+ EGCs led to a striking reduction of tumour burden in a model of azoxymethane/DSS-induced colon cancer that was much less obvious following depletion of PLP1+ EGCs." (PMID 35533467, 2022). "To verify the glioneuronal architecture, we first stained BRAFV600E/AktDD brain slices with antibodies against the glial fibrillary acidic protein (GFAP) and microtubule-associated protein 2 (MAP2) and found a strong immunoreactivity for both markers within the tumor area." (PMID 36538906, 2022). "Due to previous studies, invaded brain tissue surrounded by tumor may facilitate the positivity of GFAP." (PMID 36438949, 2022). "With the increasing grade of conventional MNSTs, we recorded a slight decrease in the expression of IHC markers Sox10, claudin-1, and GFAP, which could be the result of poorer differentiation of tumor cells in higher-grade tumors." (PMID 35622732, 2022). "Our model predicts that the exception to GFAP levels scaling with tumour growth and severity occurs late in GBM growth when levels may begin to decrease." (PMID 35919979, 2022). "Confocal imaging revealed that in addition to preserving the fluorescence of EGFP+ tumor cells and perfused lectin-649 labeled endothelial cells, each of these distinct antigens (GFAP, αSMA, and Tuj1) was robustly detected by indirect immunofluorescence following EZ Clearing and cryosectioning." (PMID 36218247, 2022). "When switched to FBS-containing medium, these tumour spheres began to adhere to the bottom of the culture dishes and initiate differentiation, spreading gradually into monolayers and expressing the marker of neuroglial cells, GFAP." (PMID 36157880, 2022). "We model the dynamic changes in serum GFAP observed with tumour growth for a ‘typical’ GBM." (PMID 35919979, 2022). "This could lead to larger errors if using population averages to convert the serum GFAP concentration to tumour volume." (PMID 35919979, 2022). "The GFAP heterogeneity observed experimentally is in good agreement with our results, but experimental data are limited and more data with more thorough quantification are required to fully quantify heterogeneity across different tumours." (PMID 35919979, 2022).